DPP4 (dipeptidyl peptidase 4)
Diseases named in the same sentence as DPP4 in open-access papers (continued):
Sharing a sentence is not in itself a finding about the gene and the disease.
diabetic retinopathy (18 papers, 2016 to 2025). "This study aimed to investigate the association of add-on dipeptidyl peptidase-4 inhibitor (DPP4i) therapy and the progression of diabetic retinopathy (DR)." (PMID 34203446, 2021). "Recent studies have shown that beyond their effect in lowing glucose, DPP-4 inhibitors mitigate DM-related microvascular complications, such as diabetic retinopathy." (PMID 33051573, 2020). "To date, limited clinical data are available regarding the effect of DPP-4 inhibitors on diabetic retinopathy." (PMID 32190049, 2020). "The clinical implications of this study suggested one potential dark side of DPP4-inhibitors, i.e., aggravation of diabetic retinopathy by increasing vascular permeability in the retina." (PMID 27381080, 2016). "The aim of this study was to investigate the effects of DPP4-inhibitors on vascular permeability and diabetic retinopathy." (PMID 27381080, 2016). "Our results suggested that DPP4-inhibitor aggravates vascular leakage in the retinas of both models: retinopathy of prematurity and diabetic retinopathy." (PMID 27381080, 2016). "A streptozotocin (STZ)-induced diabetic retinopathy model was used to elucidate the in-vivo effects of DPP4-inhibitor in actual diabetic mice." (PMID 27381080, 2016). "Moreover, DPP-4 inhibition increased the survival of islet grafts and improved diabetic retinopathy." (PMID 29507862, 2018). "Additionally, in the murine diabetic retinopathy model, DPP4-inhibitor increased the phosphorylation of Src and VE-cadherin and aggravated vascular leakage in the retinas." (PMID 27381080, 2016). "DPP4-inhibitor further aggravated retinal vascular leakage in the diabetic retinopathy model." (PMID 27381080, 2016). "In conclusion, our study raised the hypothesis that DPP4-inhibitors might aggravate diabetic retinopathy by increasing vascular permeability through the SDF-1α/CXCR4 axis, followed by Src activation and phosphorylation of VE-cadherin." (PMID 27381080, 2016). "Since retinal neovascularization is the hallmark of proliferative diabetic retinopathy in humans, we used this retinopathy of prematurity model, in addition to a STZ-induced diabetic retinopathy model, to fully evaluate the effects of DPP4-inhibitor on diabetic retinopathy." (PMID 27381080, 2016). "Moreover, the dipeptidyl peptidase-4 (DPP-4) Inhibitor could exacerbate vascular leakage from the retina by increasing phosphorylation of Src and VE-cadherin in a mouse diabetic retinopathy model." (PMID 35615279, 2022). "Therefore, on the basis of our results of increased vascular permeability caused by DPP4-inhibitor, GLP-1 agonists might have an advantage over DPP4-inhibitors in terms of concern about aggravation of diabetic retinopathy." (PMID 27381080, 2016). "However, DPP4-inhibitors might have adverse effects on diabetic retinopathy by promoting vascular leakage because DPP4-inhibitors increase active SDF-1α concentration which would activate the SDF-1α/CXCR4/Src pathway." (PMID 27381080, 2016). "There is also precedent for DPP4 function within retinal vascular homeostasis which is perturbed in murine models of both ROP and diabetic retinopathy." (PMID 37292936, 2023). "The possible use of GLP-1, of GLP-1R analogs, or of inhibitors of dipeptidyl peptidase 4 (DPP4, the GLP-1 degrading enzyme) to treat diabetic retinopathy has been investigated in both in vitro and in vivo models." (PMID 31374938, 2019). "DPP4-inhibitors, however, accumulate stromal cell-derived factor-1α (SDF-1α), a well-known inducer of vascular leakage and angiogenesis both of which are fundamental pathophysiology of diabetic retinopathy." (PMID 27381080, 2016). "We tested the hypothesis of whether DPP4-inhibitors, by stimulating the SDF-1α/CXCR4 axis and subsequently resulting in Src-mediated phosphorylation of VE-cadherin, would increase vascular permeability, which is a key process in diabetic retinopathy." (PMID 27381080, 2016).
inflammatory bowel disease (18 papers, 2018 to 2026). A spectrum of small and large bowel inflammatory diseases of unknown etiology. "Previous reports have discussed a possible association between DPP-4 inhibitors and the risk of certain autoimmune and inflammatory bowel diseases." (PMID 41464548, 2025). "HNF4A, a family member of HNF1A, was also identified as an upstream regulator of ACE2 and DPP4 gene expression in patients with inflammatory bowel disease." (PMID 35281029, 2022). "Additionally, literature indicates that patients with inflammatory bowel disease also exhibit decreased circulatory levels of CD26/DPP-4." (PMID 39390508, 2024). "A recent systematic review from 2021 suggests that DPP-4 levels may serve as a promising biomarker for monitoring inflammatory bowel disease activity." (PMID 39390508, 2024). "DPP4 has been suggested as a possible biomarker for inflammatory bowel disease (IBD)." (PMID 35060938, 2022). "In the setting of inflammatory bowel disease (IBD), dipeptidyl peptidase 4 (DPP4) and gut microorganisms have been proved to interplay, potentially influenced by dietary factors." (PMID 39684563, 2024). "To further examine possible co-expression of ACE2 and DPP4 in the ileum, we explored a microarray dataset (GEO accession GSE75214) of ileum samples from healthy individuals, as well as individuals with inflammatory bowel disease and Crohn’s disease (left)." (PMID 32902372, 2020).
leukemia (18 papers, 2003 to 2025). A malignant (clonal) hematologic disorder, involving hematopoietic stem cells and characterized by the presence of primitive or atypical myeloid or lymphoid cells in the bone marrow and the blood. "Although CD26/DPP4 surface expression in B-ALL, AML, and T-ALL was comparable to levels observed in patients with non-leukemic hematologic alterations or in healthy controls, plasma CD26/DPP4 activity was significantly higher in leukemia patients." (PMID 34885056, 2021). "Moreover, CD26/DPP4 was identified in proteomic screens of enriched organelles from the leukemia/lymphoma NK cell line YTS and of lysosomal effector compartments from non-transformed human T cells." (PMID 34885056, 2021). "Additionally, abnormally activated CXCR2 expression induces dipeptidyl peptidase IV (DPP4/CD26), a marker of CML leukemia stem cells, and inhibits the PI3K/Akt/mTOR pathway cascade." (PMID 40427609, 2025).
lung diseases (18 papers, 2007 to 2026). "Although the primary receptors of highly pathogenic CoVs, ACE2, and CD26/DPP4 are expressed on the host cells of almost all organs, these viruses mainly cause lung diseases." (PMID 34239932, 2021). "Previous studies have suggested that CD26/dipeptidyl peptidase-4 (DPP4) plays a crucial role in the pathobiological processes in lung diseases." (PMID 39684311, 2024). "Although SARS-CoV-2 and MERS-CoV commonly cause lung disease in humans, they have different target receptors, angiotensin-converting enzyme 2 (ACE2) and dipeptidyl peptidase 4 (DPP4), respectively, on the host cell surface." (PMID 36830411, 2023). "After an initial screening of the title and abstract, the full text of all the relevant articles in English language about the roles of DPP4 and DPP4 inhibitors in lung diseases were included." (PMID 34955820, 2021). "Here, we summarized the emerging roles of DPP4 and DPP4 inhibitors in lung diseases to provide new insights into clinical work." (PMID 34955820, 2021). "More evidence has shown the role of DPP4 in the pathogenesis of lung diseases, since it is highly expressed in the lung parenchyma and the surface of the epithelium, vascular endothelium, and fibroblasts of human bronchi." (PMID 34955820, 2021). "DPP4 knock-in mice were found more susceptible to MERS-CoV infections which resulted in the severe inflammatory response and lethal lung disease." (PMID 33233425, 2020). "Examination of the role of DPP-4 in pulmonary disease was previously limited to respiratory epithelial injury such as bronchial asthma." (PMID 29037205, 2017). "Recently, in related studies on DPP4 as a therapeutic target for lung diseases, it was found that DPP4 may be involved in the pathophysiology of COPD." (PMID 35629891, 2022). "Considering reports of the high expression of DPP4 in lung diseases and anti-inflammatory function of DPP4i in vitro and in vivo, we speculated that DPP4i might be a potential therapeutic candidate for SAP-ALI." (PMID 34635643, 2021). "Therefore, further experimental and clinical studies are needed to explore the role of DPP4 in lung diseases to identify novel treatment approaches." (PMID 34955820, 2021). "Thus, CD26/DPP4 is a potential therapeutic target for lung diseases that involve the dysfunction of pulmonary microvascular endothelial cells, such as ARDS." (PMID 34944016, 2021). "This narrative review summarizes recent clinical and experimental evidence on the role of DPP-1, DPP-4, DPP-9, and DPP-10 in pulmonary diseases." (PMID 42193335, 2026). "Whereas the bronchioid group is characterized by pulmonary diseases (such as TMPRSS2 and DPP4), and activated cell-surface proteins." (PMID 39346064, 2024). "Therefore, targeting DPP4 may provide a novel approach for treating lung diseases in the future." (PMID 34955820, 2021). "CD26/DPP4 is widely expressed in various cell types in lung tissues, such as Type I and II alveolar cells, alveolar macrophages, and vascular endothelial cells, and has recently been suggested as a therapeutic target in lung diseases." (PMID 39684311, 2024). "CD26/DPP4 is widely expressed in a variety of cell types in lung tissue, such as type I and II alveolar cells, alveolar macrophages, and vascular endothelia, and has been recently suggested to be a therapeutic target in lung diseases." (PMID 34944016, 2021).
pneumonia (18 papers, 2015 to 2026). An acute, acute and chronic, or chronic inflammation focally or diffusely affecting the lung parenchyma, caused by an infection in one or both of the lungs (by bacteria, viruses, fungi, or mycoplasma.). "Since SARS-Cov-2 mainly causes ‘immune storm’ and pneumonia in patients, and the expression of DPP4, an alternative receptor of SARS-Cov-2, is a prognostic factor for LUSC patients." (PMID 33614513, 2021). "Similarly, the majority of meta-analysis pooling results from clinical trials suggest that there is not a significant risk of all-cause infection, upper respiratory tract infections, or pneumonia associated with using a DPP4 inhibitor." (PMID 30310100, 2018). "Use of DPP-4 inhibitors and risk of pneumonia in T2DM patients, by sex and age." (PMID 26468883, 2015). "Use of DPP-4 inhibitors and risk of pneumonia in T2DM patients, by cumulative dose and daily dose." (PMID 26468883, 2015). "We also observed lower pneumonia-related mortality in users of SGLT2 inhibitors than in users of DPP-4 inhibitors." (PMID 41140367, 2025). "But among other hypoglycemic agents, combined use of DPP-4 inhibitor and TZD seems to have a higher risk of hospitalization for all-cause pneumonia." (PMID 36876083, 2023). "In a large, national cohort trial, the use of SGLT2 inhibitors was linked with decreased risks of total respiratory events, pneumonia, and respiratory failure among T2DM patients compared to the use of DPP-4 inhibitors." (PMID 37109700, 2023). "Bu if the patient is combined use of DPP-4 inhibitor and TZD seems to make the TZD lose their protective effect against all-cause pneumonia for reasons that are unclear." (PMID 36876083, 2023). "Compared with placebo, DPP-4 inhibitors showed generally neutral associations across respiratory outcomes, with non-significant trends toward reduced risks of pneumonia, pulmonary embolism, respiratory failure, and bronchitis." (PMID 41567683, 2025). "Firstly, rates of pneumonia were lower among users of SGLT2 inhibitors than DPP-4 inhibitors." (PMID 41140367, 2025). "Marmoset model, which has the same interaction characteristic between its DPP4 and MERS-CoV spike protein, was partially lethal and developed a progressive severe pneumonia after MERS-CoV infection." (PMID 26701103, 2015). "Another study using a Spanish general practice research database and a meta-analysis of randomized controlled trials (RCTs), on the other hand, showed no protective effects against pneumonia or respiratory infections with DPP-4 inhibitor use compared against active comparator drugs." (PMID 37891260, 2023). "Similarly, our research suggests increased reporting of these infections and pneumonia for users of DPP-4 inhibitors (as a class) compared with users of other non-insulin antidiabetic drugs." (PMID 32938499, 2020).
atrial fibrillation (17 papers, 2017 to 2025). A disorder characterized by an electrocardiographic finding of a supraventricular arrhythmia characterized by the replacement of consistent P waves by rapid oscillations or fibrillatory waves that vary in size, shape and timing and are accompanied by an irregular ventricular response. "DPP-4 inhibition contributes to atrial remodeling and improves mitochondrial function, thereby reducing the risk of atrial fibrillation which predisposes to cerebrovascular events." (PMID 40771927, 2025). "DPP-4 inhibitors also have anti-fibrotic effects, reduce the risk of atrial fibrillation, and consequently suppresses the disruption of cerebrovascular homeostasis." (PMID 40771927, 2025). "Some nationwide cohort studies in Taiwan have shown that DPP-4 inhibitors can reduce the incidence of new-onset atrial fibrillation in elderly patients." (PMID 40771927, 2025). "Another trial based on a Taiwanese multi-center healthcare provider reports a lower incidence rate of atrial fibrillation after SGLT2 inhibitor treatment compared to dipeptidyl peptidase 4 (DPP4) inhibitor treatment in more than 25,000 patients." (PMID 35163599, 2022). "The risk of atrial fibrillation has not, to our knowledge, been reported to show associations with either SGLT‐2 or DPP‐4 inhibitors, and should thus be expected to be neutral." (PMID 28771923, 2018).
hyperlipidemia (17 papers, 2014 to 2025). "Anti-diabetic drugs including metformin, alpha-glucosidase inhibitors, pioglitazone, dipeptidyl-peptidase-4 inhibitors and glucagon-like peptide 1 analogues have been shown to ameliorate postprandial hyperlipidemia." (PMID 37762244, 2023). "We also employed SS to identify the heterozygous p.V486M mutation in the DPP4 gene of the proband’s aunt (II:4, 67 years old) with T2DM, hyperlipidemia, and chronic myocarditis." (PMID 29556215, 2018). "Studies in cell cultures and animal models have demonstrated that DPP-4 inhibitors have trophic effects on pancreatic β-cells and can improve other metabolic characteristics, such as hyperlipidemia and low-grade inflammation." (PMID 29482528, 2018). "The relationship between hyperlipidemia and DPP4 activity has been studied extensively." (PMID 27654253, 2016).
acute coronary syndrome (16 papers, 2014 to 2025). Signs and symptoms related to acute ischemia of the myocardium secondary to coronary artery disease. "The acute coronary syndrome patients (n = 299) had elevated DPP4 levels than those with stable angina patients (n = 83)." (PMID 27654253, 2016). "For in vivo ventricular arrhythmia study, it would be of interest to see whether metformin alone or in combination with a dipeptidyl peptidase-4 inhibitor could reduce ventricular arrhythmias or sudden cardiac death in acute coronary syndrome patients." (PMID 33234131, 2020). "However, definitive proof of an effect of DPP-4 inhibitors in patients with acute coronary syndrome, as well as in patients with DPP-4 inhibitors therapy before the cardiovascular event is currently lacking." (PMID 29308090, 2018). "In the EXAMINE trial, alogliptin (a DPP4 inhibitor) use was associated with increased admissions for HF in T2DM patients with recent acute coronary syndromes, but the differences were not significant: HR 1.19 (95% CI: 0.89–1.58), p = 0.24." (PMID 28733630, 2017). "This concept has been recently investigated by authors, reporting that, in acute coronary syndromes, the cardiovascular outcomes were strictly correlated to postprandial GLP-1 levels independently from endogenous (DPP-4 inhibitors) vs exogenous (GLP-1 agonist) treatments." (PMID 29308090, 2018).
Cirrhosis (16 papers, 2018 to 2025). A chronic disorder of the liver in which liver tissue becomes scarred and is partially replaced by regenerative nodules and fibrotic tissue resulting in loss of liver function. "For example, it has been reported that serum DPP-4 activity is augmented in carbon tetrachloride (CCl4)-induced cirrhosis in rats." (PMID 35163991, 2022). "DPP-4 inhibitors users exhibited a significantly reduced risk of HCC (aHRs: 0.53, 95% CIs: 0.44–0.65) after adjustment for age, sex, chronic hepatitis C virus infection, cirrhosis, anti-virus drug use, and insulin use." (PMID 36831491, 2023). "Furthermore, a global correlation map of clinical and proteomic data strongly associated DPP4, ANPEP, TGFBI, PIGR, and APOE with NAFLD and cirrhosis." (PMID 30824564, 2019). "All antidiabetic drugs can be used in patients with compensated cirrhosis, but there are still no data about patients with advanced cirrhosis, especially for glitazones, incretines, DPP-4 inhibitors and SGLT-2 inhibitors." (PMID 30413050, 2018). "Metformin, thiazolidinediones, DPP-4 inhibitors, GLP-1 receptor agonists, and SGLT2 inhibitors may be useful for patients with NAFLD or NASH, but only thiazolidinediones may be able to attenuate fibrosis or even cirrhosis." (PMID 35252271, 2022).